EGFR (epidermal growth factor receptor)
Diseases named in the same sentence as EGFR in open-access papers (continued):
Sharing a sentence is not in itself a finding about the gene and the disease.
colorectal cancer (continued). "Anti-EGFR/BRAF regimens outperformed other targeted combinations in pretreated patients, reinforcing that EGFR and BRAF are pivotal therapeutic targets for BRAF-mutated colorectal cancer." (PMID 41355781, 2025). "Musarin, a polysaccharide peptide isolated from Trametes versicolor powder, downregulated the epidermal growth factor receptor-ras signaling pathway (EGFR-Ras signaling pathway) in colorectal cancer stem-like cells and inhibited the proliferation of CSC-like CD24+CD44+ HT29 cells." (PMID 40508113, 2025). "In colorectal carcinoma, EGFR (ErbB1) signaling remains a cornerstone of oncogenic drive, while the HER2 (ErbB2) and HER3 (ErbB3) axis has gained increasing recognition for its role in tumor progression, therapy resistance, and compensatory signaling when EGFR is inhibited." (PMID 41515404, 2025). "Consequently, the clinical use of BRAF V600E inhibitors in colorectal cancer necessitates the supplementary application of cetuximab, a monoclonal antibody targeting EGFR." (PMID 39337479, 2024). "For instance, it can inhibit pyroptosis and the release of interleukin-1β in response to ATP stimulation and bacterial infection, and it also reduces Lithocholic Acid-induced Interleukin-8 production in human colorectal cancer cells by inhibiting Src/EGFR and reactive oxygen species." (PMID 39205680, 2024). "Overexpression or mutation of EGFR has been linked to the development of various solid tumors, such as NSCLC, nasopharyngeal carcinoma, squamous cell carcinomas of the head and neck, and colorectal cancer." (PMID 39070179, 2024). "Anti‐EGFR antibodies have been clinically applied to colorectal cancer." (PMID 39540676, 2024). "Considering EGFR mutations at the interface, G465R and S492R are identified to be related to cetuximab resistance, while S492R does not affect panitumumab binding in colorectal cancer treatment." (PMID 38216592, 2024). "EGFR mutation is not common in colorectal cancer patients, whereas upregulation of EGFR is common in this disease." (PMID 38542291, 2024). "Interestingly, alternative ubiquitination targets of RNF43 and homologous ligase ZNRF3 at the plasma membrane include EGFR, which is deregulated by pathogenic mutations in a sub-set of CDX2-suppressed colorectal cancers." (PMID 39452477, 2024). "The co-expression of EGFR and FGFR2 linked to resistance to EGFR kinase inhibitors in esophageal cancer was reported, while the co-expression of EGFR and EPHA2 was found associated with the promotion of tumorigenesis in lung and colorectal cancer." (PMID 38338684, 2024). "EGFR also plays a pivotal role in colorectal cancer treatment." (PMID 38542291, 2024). "MTX-211 (also known as Mol 211, HY-107364), functioning as a dual inhibitor targeting both epidermal growth factor receptor (EGFR) and phosphoinositide-3 kinase (PI3K), exhibited potent in vivo growth-inhibitory effects against colorectal cancer models characterized by BRAF and KRAS mutations." (PMID 38791198, 2024). "Additionally, in colorectal cancer, EGFR’s impact on tumor grade, stage, and survival underscores its significant role in cancer progression." (PMID 39193333, 2024). "Targeted therapy for colorectal cancer mainly focuses on the EGFR and VEGF signaling pathways." (PMID 39555098, 2024). "Additionally, the amplification of HER2 is proposed as a resistance mechanism to EGFR TKIs in NSCLC patients, and anti‐EGFR monoclonal antibody cetuximab in patients with colorectal cancer." (PMID 39184861, 2024). "Clinical studies have indicated that a combination of anti‐EGFR targeted therapy and KRAS c.34G>T (p.G12C) inhibitor could be an effective treatment strategy in KRAS c.34G>T (p.G12C)‐mutated colorectal cancer." (PMID 39039804, 2024). "To understand whether this correlation is also valid in other cancers, we investigated the correlation between the CI of EGFR inhibitor/SN-38 combination with ABCG2 expression in colorectal cancer cells using data reported in the literature." (PMID 39033209, 2024).
colorectal cancer (continued). "Most colorectal cancer cells depend on EGFR/KRAS/BRAF/MAPK-signaling pathway activation." (PMID 38193944, 2024). "In colorectal cancer patients receiving anti‐EGFR monoclonal antibody therapy, RAS and EGFR‐extracellular domain mutations were detected in ctDNA 10 months before radiographic progression, and these mutations disappeared after discontinuation of anti‐EGFR therapy." (PMID 39184861, 2024). "Considering the reported EGFR overexpression in 25% to 82% of colorectal cancer cells, it is implied from this evidence and our findings that PEITC, BITC, and SFN might hold promise in cancer treatment by inhibiting the expression of Erb‐B family factors." (PMID 39479720, 2024). "Similarly to BRAF V600 inhibitors, these drugs appear to be more efficacious for colorectal cancer when administered in combination with anti-EGFR antibodies." (PMID 38612902, 2024). "We observed a strong correlation between the genome-wide DNA methylation status (GWMS) and the clinical outcomes of anti-EGFR antibodies, and we found that high-methylated colorectal cancer (HMCC) was refractory to anti-EGFR antibodies compared with low-methylated colorectal cancer (LMCC)." (PMID 38862615, 2024). "The role of EGFR in colorectal cancer liver metastasis is particularly critical." (PMID 39581873, 2024). "However, when ERK activation is inhibited by KRASG12C inhibitors, EGFR signaling acts as the dominant mechanism of colorectal cancer resistance to KRASG12C inhibitors." (PMID 38921956, 2024). "In colorectal cancer, it was found that AMSCs-derived exosomes could significantly reduce the mRNA levels of epidermal growth factor receptor (EGFR) and aquaporin 5, which plays an important role in cancer progression by promoting tumor cell motility." (PMID 39697630, 2024). "A CD3(scFv)/EGFR(Nb)/EpCAM(Nb) trispecific T-cell engager (TriTE) was developed to target colorectal cancer cells that could activate T cells and lyse colorectal cancer cells." (PMID 36761751, 2023). "Over-expression of EGFR is found in 65–75% of patients with advanced colorectal cancer." (PMID 37296986, 2023). "Hypomagnesemia is evidenced in cancer patients after cisplatin-based chemotherapies, and it has emerged as the most notable adverse effect of the anti-epidermal growth factor receptor (EGFR) monoclonal antibody, cetuximab, which is used widely for the treatment of advanced colorectal cancer cells." (PMID 37892239, 2023). "However, a decrease was apparent in our tumorous livers when comparing with matched non-tumorous samples from same donors, in line with immunohistochemistry data indicating that EGFR is lost in several metastasising primary colorectal cancer tumours." (PMID 36890818, 2023). "The phase III TRUSTY trial is currently underway to confirm the non-inferiority of TFTD plus Bmab to S-1 plus irinotecan/FOLFIRI plus Bmab in patients with unresectable refractory colorectal cancer and those who are intolerant to first-line fluoropyrimidines, OX, Bmab, and anti-EGFR antibodies." (PMID 36765099, 2023). "The emergence of anti-EGFR therapy has revolutionized the treatment of colorectal cancer (CRC)." (PMID 37310146, 2023). "However, this is one of the few reports directly comparing the incidence of thromboembolism between VEGF and EGFR inhibitors during first-line treatment of unresectable advanced recurrent colorectal cancer in Japanese patients." (PMID 37394446, 2023). "Anti-EGFR mAb induces EGFR internalization in colorectal cancer (CRC) cells." (PMID 37765202, 2023). "Notably, in human colorectal cancer cell lines, the EGFR-induced tyrosine phosphorylation of PPARδ led to the recruitment of HSP90, and its stabilization conferred chemoresistance to the EGFR inhibitor gefitinib." (PMID 37833991, 2023).
colorectal cancer (continued). "This problem is evident in colorectal cancer, in which, despite the advances in therapeutic options, such as EGFR inhibitors and drug combinations using EGFR inhibitor plus VEGF inhibitor/MEK inhibitor/BRAF inhibitor, the mortality rate remains high for cancer-related deaths." (PMID 37049976, 2023). "However, CD9, another canonical EV marker protein, is associated with EGFR-positive EVs; most CD9-positive EVs are EGFR-positive in colorectal cancer cell DiFi, and approximately 74% of EGFR-positive EVs are CD9-positive in glioma cancer cell U373vIII." (PMID 37823055, 2023). "In addition, the first-line chemotherapy for patients with RAS wild-type colorectal cancer includes a combination of the anti-epidermal growth factor receptor (EGFR) antibodies, cetuximab and panitumumab, in addition to conventional chemotherapy." (PMID 37069612, 2023). "EGFR overexpression or mutations are frequently observed in cancer types such as non-small cell lung cancer (NSCLC), head and neck squamous cell carcinoma (HNSCC), colorectal cancer, gastric cancer and breast cancer." (PMID 38136430, 2023). "To investigate whether MARM2.0 could predict the responses of BRAFV600E colorectal cancers to RAFi, we collected data from HT29 cells, which carry a heterozygous BRAFV600E mutation and have high EGFR expression (similar to A375 EGFR‐CRISPRa cells)." (PMID 36700386, 2023). "For example, AFM-24, a BiTKe engaged IgG1-scFv fusion antibody of CD16 with epidermal growth factor receptor (EGFR) activating NK cells through CD16 receptor for targeting EGFR, is now in clinical Phase II for treating patients with lung, colorectal cancer, and metastasis." (PMID 37190251, 2023). "EGFR-targeted therapy was confirmed to increase overall survival by 10–20% in colorectal cancer." (PMID 37762323, 2023). "In addition, EGFR-specific N-glycosylations are correlated with the disease state/progression of colorectal cancer, thus, EGFR-related N-glycans were considered for the docking process." (PMID 37259433, 2023). "However, the inability of type I1⁄2 inhibitors to fully inhibit homo‐ and hetero‐dimer RAF kinases is a primary mechanism of drug resistance in cancers with sustained RAS‐GTP signaling, including EGFR‐driven signaling in BRAFV600E/K colorectal cancer." (PMID 36700386, 2023). "Thus, the use of anti-EGFR antibodies in second-line treatment is expected to be limited to approximately 10% of colorectal cancers." (PMID 37760533, 2023). "Interestingly, the GAT model was able to identify genes related to anti-EGFR therapy (Cetuximab) resistance in colorectal cancer." (PMID 37114077, 2023). "EGFR inhibitor cetuximab can be used as a superior chemotherapy drug for advanced colorectal cancer patients without KRAS mutation." (PMID 37777749, 2023). "Moreover, monoclonal antibodies targeting EGFR and its downstream signaling pathways were reported in treating colorectal cancer, head and neck carcinomas, but few reports comprehensively investigated the clinical outcomes in NSCLC." (PMID 36910653, 2023). "Indeed, EGFR targeted therapy was found to increase overall survival by 10–20% in colorectal cancer." (PMID 36979659, 2023). "For colorectal cancer, CodeBreak 300 is an actively recruiting Phase 3 clinical trial for refractory metastatic cancer, evaluating Sotorasib in combination with Panitumumab (EGFR inhibitor) versus either TAS-102 or Regorafenib." (PMID 37190303, 2023). "The linear GE11 dodecapeptide YHWYGYTPQNVI was selected against the purified human EGFR protein and tested in EGFR-positive cancer cells and tumor xenografts and was further conjugated to different drug delivery nanocarriers for targeting liver, ovarian and colorectal cancers." (PMID 37048151, 2023). "Although to different degrees, EGFR expression was observed in up to 82% of colorectal carcinomas." (PMID 37895912, 2023). "Cetuximab is one of the anti-EGFR drugs used to treat colorectal cancer." (PMID 36005935, 2022).
colorectal cancer (continued). "Our results indicate that the formation of a complex between EGFR, EphA2, and Ephexin1 plays an important role in lung and colorectal cancers, and that inhibition of this complex may be an effective target for cancer therapy." (PMID 35668076, 2022). "For example, G12C KRAS inhibitors cause clinical benefit in KRAS G12C-driven NSCLC but not colorectal cancer and this is related to feedback loops involving EGFR signaling." (PMID 35368084, 2022). "Cetuximab is not indicated in EGFR expression colorectal cancer with a Ras‐mutant due to treatment‐related toxicity; EGFR amplification co‐occurred with an NRAS (p.G12S) mutation in a single tumor." (PMID 35229492, 2022). "The presence of EGFR-expressing CTCs was shown in the majority of colorectal cancer patients." (PMID 35035479, 2022). "One well-known example is the anti-EGFR antibody and colorectal cancer." (PMID 35740492, 2022). "Non KEGG pathway was significantly enriched for the parental genes of the DE circRNAs, the three most enriched KEGG pathways were apoptosis (oas04210), epidermal growth factor receptor (EGFR) tyrosine kinase inhibitor resistance (oas01521), and colorectal cancer (oas05210)." (PMID 36425117, 2022). "Since EGFR was reported to mediate antitumor effect of CB2 activation, we explored whether EGFR was involved in the antitumor effect of CB1 in colorectal cancer." (PMID 35641479, 2022). "In advanced colorectal cancer, all the patients with MAP2K1 mutation treated with anti-EGFR, anti-EGFR combined with MEK and BRAF inhibitors, or anti-EGFR combined with ERK inhibitors, showed disease progression, where the MAP2K1 mutation was associated with poor response to targeted therapy." (PMID 35186740, 2022). "A large amount of evidence indicates that the presence of BRAFV600E mutation is related to the poor prognosis of patients with colorectal cancer, which is non-responsive to anti-EGFR treatment." (PMID 35864467, 2022). "Colorectal cancers that harbor a mutation in K-ras or N-ras are unlikely to benefit from anti-EGFR antibodies such as cetuximab or panitumumab." (PMID 35740492, 2022). "This study investigated whether the epidermal growth factor receptor (EGFR) represents a suitable target for preoperative antibody treatment of colorectal cancer patients undergoing surgery." (PMID 35035479, 2022). "In colorectal cancer, all the tumor types being treated were adenocarcinoma and all patients were treated with a modified standard cytotoxic chemotherapy (78.4%) or additional EGFR monoclonal antibody cetuximab (21.6%)." (PMID 35402275, 2022). "Since the importance of EGFR amplification has already been established as a precision medicine target in other cancers, such as colorectal cancers, HNSCC, and NSCLC, our findings may also open new therapeutic approaches in future brain tumor therapy." (PMID 35453544, 2022). "Furthermore, among colorectal cancer cells, miR-141- has been proven to reduce cell growth and induce apoptosis and differentiation of colorectal cancer cells by targeting EGFR." (PMID 36158660, 2022). "Furthermore, EFNA5 promotes the malignant progression of pancreatic cancer but played a tumor suppressor role in glioma by inhibiting EGFR, tumor invasiveness, and metastasis in hepatoma and colorectal cancer." (PMID 35945523, 2022). "CB1 and EGFR expression were examined in colorectal cancer cell lines." (PMID 35641479, 2022). "Studies have shown that EGFR is highly expressed or abnormally expressed in many solid tumors of epithelial origin, such as head and neck cancer and colorectal cancer, which is related to cancer cell proliferation, tumor angiogenesis, tumor invasion, and metastasis." (PMID 35433839, 2022). "Combined with the fact that anti-EGFR mAbs are already clinically used to treat metastasized colorectal cancer, we hypothesize that EGFR also represents an appropriate target for preoperative antibody treatment." (PMID 35035479, 2022).
colorectal cancer (continued). "In colorectal cancer, consensus molecular subtypes (CMSs) and colorectal cancer typing (CRCAssigner) based on mRNA expression profiles predict the efficacy of bevacizumab and anti-EGFR in RAS wild-type advanced colorectal cancer." (PMID 36238279, 2022). "For example, patients with advanced colorectal cancer without canonical mutations in the RAS/RAF pathway can be treated by a combination of chemotherapy plus antiepidermal growth factor receptor (EGFR) monoclonal antibody." (PMID 35741030, 2022). "Furthermore, this manuscript aims to assess the main targets of these natural derivatives with particular attention on Epidermal growth factor receptor in breast, prostate and colorectal cancers." (PMID 36428610, 2022). "We showed that CB1 was downregulated while EGFR was upregulated in colorectal cancer cells." (PMID 35641479, 2022). "This could explain more than 70% of the colorectal cancer cases with ineffective anti-EGFR treatment." (PMID 35433839, 2022). "Using molecular docking, a study to find possible applicable curcumin targets for treating colorectal cancer showed that curcumin could stably combine with EGFR, STAT3, and AKT1." (PMID 36297027, 2022). "Similar to NSCLC, EGFR is overexpressed in approximately 50 ~ 80% of colorectal cancers." (PMID 36209184, 2022). "In EGFR-expressing colorectal cancer (CRC), the mainstay of treatment is EGFR-targeting antibodies." (PMID 35756680, 2022). "Examining the phenotypes of KRAS mutant and wild‐type colorectal cancer cells during anti‐EGFR treatment may provide significant insights into drug resistance." (PMID 37323700, 2022). "Currently, the National Comprehensive Cancer Network (NCCN) advises that colorectal cancer patients with any KRAS or NRAS mutation will not benefit from anti-EGFR therapy." (PMID 35045886, 2022). "Uncertain molecular weight and a complex composition are problems that have been solved through studies on its structure, and it was demonstrated to have strong anti-proliferation activity on colorectal cancer in vitro and in vivo via interaction with EGFR signaling pathway." (PMID 36359361, 2022). "In colorectal cancer, concordance of KRAS mutations vary between 86.4% and 92%, estrogen receptor 1 (ESR1) mutation in metastatic breast cancer is concordant in 74.3% of patients and actionable EGFR in NSCLC was reported to be concordant in 79% of patients." (PMID 35741030, 2022). "Therefore, evaluating K-ras mutation status is virtually mandatory when administering anti-EGFR antibody agents to colorectal cancer patients." (PMID 35740492, 2022). "In addition to EGFR expression levels, ligand binding to EGFR is important in functions that modulate various aspects of colorectal cancers." (PMID 35455247, 2022). "To investigate the importance of Ephexin1, EGFR and EphA2 in lung and colorectal cancer patient tissues, we analyzed the TMA database for lung and colorectal tissues composed of carcinomas and metastatic tumors of different grades to determine the expression levels of each of the three proteins." (PMID 35668076, 2022). "STAT3 also increases the survival of EGFR+ cancer stem cells in colorectal cancer." (PMID 35681787, 2022). "Approximately 80% of colorectal carcinomas show overexpression of EGFR." (PMID 35035479, 2022). "In some cases, recommendations were given that were clearly not indicated, such as the administration of anti-EGFR substances in KRAS-mutated colorectal carcinoma." (PMID 34436668, 2022). "Besides, monoclonal therapies such as Panitumumab and Cetuximab [monoclonal antibodies directed to the epidermal growth factor receptor (EGFR)] have demonstrated clinical efficacy in patients with colorectal cancer in advanced stages." (PMID 34123772, 2021).